MTOR (mechanistic target of rapamycin kinase)
Diseases named in the same sentence as MTOR in open-access papers (continued):
Sharing a sentence is not in itself a finding about the gene and the disease.
cancer (continued). "Crosstalk between mTOR and Hh was present in several systems and it has been hypothesized that mTOR and Hh are entangled in the metastasis process of various cancers." (PMID 34203598, 2021). "Additionally, cancer cells still maintain mTOR activation even although the actions of PI3K and AKT are suppressed." (PMID 34768941, 2021). "Interestingly, the rapamycin-mediated inhibition of mTOR also resulted in an enlarged population of dormant cancer cells and, furthermore, increased their resistance to chemotherapy." (PMID 34832087, 2021). "To explore other possible mechanisms, we attempted to analyze the correlation of BICD1 downregulation with a couple of markers involved in various pathways associated with cancer progression, including the immune checkpoint, MET, STAT, and MTOR pathways, in the TCGA LGG cohort." (PMID 34439934, 2021). "Individual or combined use of small molecule inhibitors targeting PI3K, AKT, and mTOR, three main nodes of PI3K/AKT/mTOR signaling pathway, could achieve therapeutic effect on cancers." (PMID 34568005, 2021). "Mutations of mTOR signaling components provide cancer cells with a selective growth advantage with respect to normal cells." (PMID 33916707, 2021). "Given the fact that leptin and adiponectin regulate autophagy and mTOR activation, these adipokines may play a multifaceted role in cancer cell-specific glutamine metabolism." (PMID 33535537, 2021). "Serving as an antiapoptotic regulator, the hyperactivation of PI3K/Akt/mTOR axis prevents the initiation of intrinsic pathway mediated apoptosis by phosphorylating downstream Bax and Bad, provoking resistance to apoptotic signals of cancer cells." (PMID 34691211, 2021). "Importantly, we firstly found MSC‐derived exosomal miR‐21‐5p promotes OS proliferation and invasion by targeting PIK3R1 and activity of cancer‐related PI3K/Akt/mTOR signalling pathway." (PMID 34741385, 2021). "However, effective pan-mTOR inhibition is eligible as mTORC2 is supposed to be a promising target for anti-cancer therapy." (PMID 35096817, 2021). "Importantly, in the context of cancer pathogenesis, human GOLPH3 function has been associated with enhanced AKT/mTOR signaling, although the precise biochemical basis for its activity remains to be determined." (PMID 34571985, 2021). "Previous studies confirmed that PIK3R3 could regulate the AKT/mTOR pathway, promoting cancer progression." (PMID 34961815, 2021). "Dysregulations in the mTOR pathway were observed in human diseases, especially certain cancers." (PMID 34812264, 2021). "The mTOR pathway plays one of the most fundamental roles in cancer development." (PMID 35008889, 2021). "The PI3K/Akt/mTOR signaling pathway is one of the major aberrantly activated intracellular pathways in human cancers, which plays an important role in the regulation of tumor cell proliferation, survival, response to stress, metabolism, motility, angiogenesis, and resistance to therapies." (PMID 34199959, 2021). "Indeed, upregulation of mTOR signalling has been demonstrated to promote resistance to anti-cancer therapies by enabling escape from cell death." (PMID 34283054, 2021). "mTOR inhibition by rapamycin can sensitize cancer cells to radiotherapy." (PMID 33640883, 2021). "Although inhibition of mTOR promotes cancer cell death by promoting apoptosis and creating nutrient deprivation conditions in cancer cells, mTORC1 blockade can efficiently enhance prolonged protective immunity by stimulating the generation of long-lived protective memory T cells." (PMID 35250965, 2021). "Also, the knockdown of BCAT1 or the administration of leucine activated mTOR signaling, inhibited autophagy, and increased cisplatin sensitivity in cancer cells in vivo." (PMID 33568627, 2021).
cancer (continued). "Until today, although several PI3K/Akt/mTOR inhibitors have been studied in clinical trials in cancer patients, only a few of them (e.g., temsirolimus, everolimus, copanlisib) have been approved for clinical use in the treatment of different cancers." (PMID 34073042, 2021). "mTORC1 functions as a downstream effector for many frequently mutated oncogenic pathways including the PI3K/AKT and Ras/RAF/MEK/ERK (MAPK) pathways, and mTOR signaling is hyperactive in a range of 40–90% in different tumor entities, which makes mTOR an attractive target for cancer therapy." (PMID 33572326, 2021). "Akt/mTOR signaling activation ultimately causes autophagy repression in cancer cells and increases NSCLC development, rendering resistance of NSCLC cells to various cancer therapies and leading to a poor prognosis." (PMID 33777755, 2021). "Due to its characterized activity, mTOR has been recognized as a target for cancer therapy." (PMID 34458019, 2021). "The activated PI3K/Akt/mTOR pathway is also considered a typical feature of cancer." (PMID 34371964, 2021). "The PI3K/AKT/mTOR axis is one of the most frequently dysregulated pathways in cancer." (PMID 34658878, 2021). "mTOR is primarily involved in the regulation of cell proliferation and cancer progression." (PMID 33802643, 2021). "Numerous studies have implicated a noncanonical role of PI3K/AKT/mTOR signaling in regulating GLI proteins in multiple cancers." (PMID 34572373, 2021). "However, mTOR-targeted cancer therapies still have significant challenges because of the anticancer efficacies of mTOR inhibitor monotherapy are limited in clinical treatment 23-25." (PMID 33754064, 2021). "The mTOR pathway has become a therapeutic target for cancer therapy." (PMID 35372372, 2021). "In addition, pathway-enrichment analyses showed that methylation modifications in P0 and P7 heart tissues were significantly associated with focal adhesion, the Notch signaling pathway, the mTOR signaling pathway, and pathways in cancer." (PMID 33829047, 2021). "Moreover, oncoproteins of HPV and EBV can lead to the development and progression of cancer via commonly linked signaling pathways including WNT/β-catenin, JAK/STAT/SRC, PI3k/Akt/mTOR, and/or RAS/MEK/ERK." (PMID 34360884, 2021). "Our initial findings with the anti-NB efficacy of MYCN/mTOR inhibition on neurospheres and stem cell markers indicate that individual or combined inhibition of MYCN/mTOR might target cancer stem cells - potentially minimizing recurrence of NB." (PMID 34565342, 2021). "Mutations in the mTOR gene are rare, and on the interrogation of the Institute for Personalized Cancer Therapy (IPCT) database in MD Anderson Cancer Center, we noted a frequency of 1.35% of 20,150 patients screened (platforms included CMS400, STGAv1, STGA DNA2018, and LBPv1)." (PMID 34853384, 2021). "It was also reported that AICAR, a specific activator for AMPK and rapamycin, an inhibitor of mTOR, could successfully suppress the cancer cachectic muscle atrophy." (PMID 33803685, 2021). "However, based on the proposed mechanism of stressors synergy, a large number of ER stress modulators or ROS modulators have the potential to induce the apoptosis in cancer cells in combination with mTOR or other pathways inhibitors." (PMID 34502310, 2021). "However, no study has been performed so far to investigate the role of genistein on regulators of mTOR and Nrf2 pathways in different types of cancer." (PMID 34289845, 2021). "Activation of mTOR inhibits autophagy, which is a cell survival mechanism; everolimus may paradoxically encourage cancer cell survival via stimulation of autophagy." (PMID 34944946, 2021).
cancer (continued). "The compound blocks the mTOR (mammalian target of rapamycin) pathway in cancer cells." (PMID 34586597, 2021). "It has been confirmed that the inhibition of the PI3K/Akt/mTOR signaling pathway has exhibited encouraging outcomes in various types of cancer, especially hematological malignancies, and might be a potential therapeutic approach for T-ALL." (PMID 34572904, 2021). "This phenomenon indicates that mTOR exerts a great effect on regulating the progression of cancer." (PMID 33819917, 2021). "Interestingly, recent data demonstrate that metformin is an AMPK activator and mTOR inhibitor that suppresses CSCs in some cancers." (PMID 33828530, 2021). "Activation of AKT/mTOR signaling promotes glycolysis in cancer cells." (PMID 33994864, 2021). "mTOR hyperactivity is characteristic for many cancers, especially in the worst cases." (PMID 34360785, 2021). "Based on these, we speculated that the 4-MTBITC modulate DMBA induced glycolytic pathway and hypoxia pathway by downregulating the expression of HIF-1α and mTOR along with some amino acids that are needed for cancer growth." (PMID 34447314, 2021). "Activation of the PI3K/AKT/mTOR pathway is a common feature of a wide range of human cancers." (PMID 34975466, 2021). "Akt stimulates SREBP1c-mediated lipogenesis via the mTOR pathway in cancer." (PMID 34158007, 2021). "Univariate analysis suggested that, compared with the other cancer hallmarks such as PI3K/AKT/mTOR signaling, apoptosis, EMT, G2M checkpoint, TGF-beta signaling, angiogenesis, and hypoxia, glycolysis and immune response were the most significant risk factors affecting the survival of UM patients." (PMID 34630418, 2021). "IGF-1 signals some of the same pathways as insulin, including PI3K, ERK, AKT, and mTOR, which could increase cancer cell proliferation and impair apoptosis." (PMID 33477579, 2021). "Several mTOR inhibitors (mTORi) are approved for the treatment of many types of cancer." (PMID 34421360, 2021). "Several mTOR inhibitors are approved for the treatment of cancers." (PMID 33754064, 2021). "In cancer cells, mTOR serves as the major negative regulator of autophagy." (PMID 34768941, 2021). "The crosstalk between the RAS/ERK and mTOR signaling pathways to positively and negatively regulate one another is well documented, while the simultaneous inhibition of both pathways induced an anti-proliferative effect on different cancer cells." (PMID 34049576, 2021). "To evaluate the molecular mechanisms leading to the cytotoxic effect of curcumin and resveratrol and their different regulation of autophagy, we explored the activation of the PI3K/AKT/mTOR pathway, which is activated and involved in cell survival of Her-2/neu-overexpressing cancers." (PMID 34832850, 2021). "Thus, progranulin regulates proliferation, at least in part, through the mTOR independent signaling pathway in the hematopoietic cancer cells." (PMID 33490663, 2021). "We wondered if Maf1, a poorly studied mTOR effector could also have roles in radio-resistance in cancer cells." (PMID 33640883, 2021). "mTOR/PI3K dual-targeted therapy has shown promise in managing various cancers." (PMID 34462635, 2021). "Kahweol, a coffee-specific diterpene, induced apoptosis in human epidermal growth factor receptor 2-overexpressing cancer cells by suppressing the PI3K/Akt/mTOR/sterol regulatory element-binding transcription factor (SREBP) 1 signaling pathway that regulates fatty acid synthesis." (PMID 34343190, 2021).
cancer (continued). "This phytocompound can affect the cell cycle of cancer cells, reduce cell cycle activators, especially cyclin B, cdk1, E-cadherin, and N-cadherin and activate multiple cellular pathways, inhibit the Akt-mTOR signaling pathway thereby inhibiting the proliferation of cancer cells." (PMID 34577581, 2021). "The present findings suggest that the targeted inhibition of downstream effectors (e.g., RAF, MEK, ERK, PI3K, AKT, and mTOR) or combinations thereof may be a more rational and effective approach for the treatment of cancers driven by KRAS Q61H." (PMID 34725361, 2021). "The efficacy of targeted mTOR pathway therapies for cancer is currently well established." (PMID 34194607, 2021). "In addition, mTOR signaling pathways are critically involved in regulating metastasis cascade in many kinds of cancers." (PMID 34671559, 2021). "Therefore, from the perspective of cancer therapy, it will be crucial to identify the dosage and administration schedule of mTOR inhibitors necessary to favor memory CD8+ T cell generation without affecting effector expansion." (PMID 33802831, 2021). "In addition, branched-chain amino acids or leucine treatment inhibited cisplatin- or BCAT1-mediated autophagy and increased cisplatin sensitivity by activating mTOR signaling in cancer cells." (PMID 33568627, 2021). "Examples are metformin, which in recent years has been gaining in importance as a CRM, especially in cancer therapy Additionally, rapamycin would be an ideal candidate due to its strong inhibitory effects on mTOR; however, it has strong immunosuppressive effects." (PMID 34769059, 2021). "The liver kinase B1 (LKB1)-dependent activation of AMPK and reduction of mammalian target of rapamycin (mTOR) activity may be significant contributors to the inhibitory effects of metformin on cancer cell growth and proliferation." (PMID 34733783, 2021). "Since inhibitors of AKT/mTOR represent potential agents in human cancers, the newly identified PRMT4/AKT/mTOR axis may serve as both a prognostic factor and therapeutic target in HCC." (PMID 34522186, 2021). "Thus, we analysed the activity of TLRs in well-known cancer hallmark pathways in KIRC, including TSC/mTOR, RTK, RAS/MAPK, PI3K/AKT, hormone ER, hormone AR, EMT, DNA damage response, cell cycle, and apoptosis pathways." (PMID 34531911, 2021). "Numerous studies have demonstrated that the expression of MMP2 and MMP9 in cancer cells could be directly mediated by activation of the PI3K/AKT/mTOR pathway." (PMID 34758823, 2021). "Furthermore, activity in the mTOR pathway, a major regulator of cancer metabolism, was significantly higher in group 3 than in group 1." (PMID 34422660, 2021). "Therefore, MTOR itself as well as genes coding for upstream activators of mTORC1, such as AKT1, EGFR, or PTEN, are frequently mutated in cancer." (PMID 34206503, 2021). "The new research had speculated that TTK could regulate the proliferation and apoptosis of cancer cells via Akt-mTOR signaling pathway." (PMID 34187556, 2021). "Importantly, the paradoxical effect of mTOR inhibitors on immunity has also been observed in cancer patients where the rapamycin analog everolimus simultaneously promoted high expansion of regulatory CD4+ T cells and activated tumor-specific Th1 immunity." (PMID 33802831, 2021). "Additionally, several groups demonstrated anti-cancer effect of mTOR inhibitors in HNSCC xenografts either as a single agent or when combined with chemotherapy/radiotherapy 56-58." (PMID 34659543, 2021). "The mTOR pathway is dysregulated in several human disorders, including cancer." (PMID 33754064, 2021). "Some studies showed that mTOR signal could regulate the expression of P-gp and affect the drug resistance of cancer cells." (PMID 34856955, 2021).
cancer (continued). "The PI3K-Akt-mTOR pathway is an interconnected cellular signaling pathway that is crucial in many cellular processes including growth and survival, nutrient uptake, anabolic reactions as well as in pathological conditions, particularly cancers." (PMID 33814008, 2021). "PI3K/AKT/mTOR pathway is noted to be upregulated in Ven resistant cancer cells." (PMID 33199836, 2021). "Cancer hallmark and immune signature analysis in our study revealed that the high-risk group of the lncRNA signature largely concentrated in DNA repair, PI3K/AKT/MTOR signaling pathway, glycolysis and immunologic characteristics in HCC." (PMID 34237706, 2021). "The KEGG pathway enrichment analysis showed that module 1 was mainly associated with the cell cycle; module 2 was mainly associated with cancer pathway, ErbB signalling pathway, PI3K-Akt signalling pathway, mTOR signalling pathway; and module 3 was associated with PI3K-Akt signalling pathway." (PMID 34809653, 2021). "More than 70% of cancers are known to result in hyperactivation of mTOR." (PMID 34123955, 2021). "The PI3K/AKT/mTOR pathway controls physiological processes such as cell growth and metabolism, proliferation, migration, survival and protein synthesis and is frequently hyper-activated in many types of human cancer." (PMID 34395258, 2021). "Recently, a large number of literature reports on the potential use of plant extracts to inhibit cancer cell proliferation by targeting components of the PI3K/AKT/mTOR signaling pathway indicating how this is an important field of research in continuous expansion." (PMID 34044827, 2021). "The relevant signaling pathways in PTEN-deficient cancer cells treated with the PI3K/mTOR inhibitor BEZ235 were screened using a phosphokinase array, and further validated following treatment with multiple PI3K/AKT/mTOR inhibitors or AKT knockdown." (PMID 33431808, 2021). "Collectively, these results reveal that PPP is an upstream regulator of AMPK, ACC1, and mTOR in PCa; therefore, targeting 6PGD could impede multiple cancer-promoting metabolic pathways." (PMID 34382934, 2021). "In more than 70% of cancer, mTOR is activated and promotes neoplastic growth and progression." (PMID 33390782, 2021). "In addition, flavonoids are promising anti-cancer agents that target the inflammatory PI3K/AKT/mTOR/p70S6K and ERK/MAPK signaling pathways." (PMID 34950252, 2021). "Consequently, caloric restriction builds a connection between aging and cancer: It has been indicated that caloric restriction increases lifespan via modifying the mammalian Target of Rapamycin (mTOR)-pathway, insulin/IGF-1 like signaling and sirtuins." (PMID 33401659, 2021). "Furthermore, ANRIL promotes GLUT1 and LDHA expression, resulting in the upregulation of glucose uptake and the promotion of cancer progression via the Akt/mTOR pathway." (PMID 34072826, 2021). "Although single-target inhibitors of either the PI3K/Akt/mTOR pathway or HDACs would be good drug candidates for cancer therapy, their demonstrated efficacies are limited due to their unfavorable pharmaceutical activities, toxicity, and crossover inhibition of other lipid and protein kinases." (PMID 33663586, 2021). "mTOR plays a key role in regulating cancer cell apoptosis and autophagy." (PMID 34221974, 2021). "Moreover, several individual miRNAs (miR-1, miR-21, miR-143 and miR-125b (Ge, sun & Chen, 2011)) have been confirmed to be regulated by mTOR signaling, which are known to participate in some physiological functions, including cancer." (PMID 33520467, 2021). "Indeed, constitutive activation of mTOR-regulated pathways is now considered as a potent inducer of tumor growth and cancer cell survival." (PMID 34634301, 2021). "In light of this evidence, it is clear that targeting mTOR could have important clinical benefits for cancer therapy." (PMID 33407885, 2021).